INS (insulin)
Diseases named in the same sentence as INS in open-access papers (continued):
Sharing a sentence is not in itself a finding about the gene and the disease.
metabolic disorders (continued). "Brown adipose tissue with its constituent brown adipocytes is a promising therapeutic target in metabolic disorders due to its ability to dissipate energy and improve systemic insulin sensitivity and glucose homeostasis." (PMID 28957413, 2017). "As IR is a part of a cluster of metabolic disorders and the majority of insulin-stimulated glucose disposal takes place in muscle tissue, we focused on associations between IR and BC parameters." (PMID 28932748, 2017). "Consistently, the patients presenting DSPN were significantly older, showed worsening renal markers, and presented a more advanced metabolic disease (insulin treatment)." (PMID 28724059, 2017). "It is well known that adult patients with GHD show a tendency towards metabolic disorders (higher body mass, unfavourable lipids, and increased leptin and insulin concentrations) and that they return to normal levels following GH treatment." (PMID 28596789, 2017). "Type 2 DM (T2DM) describes a group of metabolic disorders characterized by defects in insulin secretion and insulin sensitivity." (PMID 28929122, 2017). "DM is a complex metabolic disorder that develops due to inadequate insulin production or ineffective insulin utilization by insulin target cells in muscle, fat and the liver." (PMID 28253317, 2017). "Pro-inflammatory factors for metabolic disorders such as serum insulin, leptin, and resistin were positively correlated with serum stearic acid and γ-linolenic acid simultaneously." (PMID 28317846, 2017). "Prior to the development of a severe metabolic disease, three interacting components are abnormal: (a) lipids are elevated, (b) basal or fasting insulin is elevated (HI) and (c) IR is present." (PMID 28466412, 2017). "It has also been shown that BGP-15 is an insulin sensitizer in an olanzapine-induced metabolic disorder in human phase II studies, and also in insulin-resistant patients." (PMID 28046125, 2017). "Recently, they have been demonstrated to maintain insulin-sensitizing and antidiabetic properties, and they serve as an alternative treatment for metabolic diseases." (PMID 28720829, 2017). "The prequel to severe metabolic disease includes three interacting components that are abnormal: (a) IR, (b) elevated lipids and (c) elevated basal insulin (HI)." (PMID 28466412, 2017). "Extracellular vesicles (EVs) are released from adipocytes and have been proposed to be involved in adipocyte/macrophage cross talk and to affect insulin signaling and transforming growth factor β expression in liver cells leading to metabolic disease." (PMID 28868048, 2017). "IR is a general metabolic disorder that is attributable to the inefficient function of insulin in skeletal muscle, liver and/or adipose tissue." (PMID 29187178, 2017). "In China’s National Diabetes and Metabolic Disorders Study, 81% of those who self-reported DM also reported using insulin or oral hypoglycaemic medicines." (PMID 28077072, 2017). "Particularly, bioinformatics analysis revealed that insulin signaling pathway is the central way involved in the progression of metabolic disorders." (PMID 27597954, 2016). "To further analyze the relationship between serum FGF21 levels and metabolic disorders, we assessed its correlation with serum lipids, glucose, and insulin." (PMID 27190511, 2016). "HFD feeding in rats results in fat accumulation in the liver as well as insulin resistance, pathophysiologic features that are analogous to those of human clinical metabolic disease." (PMID 27796348, 2016). "This pathology is defined as a metabolic disorder characterized by chronic hyperglycemia with disturbances in the metabolism of carbohydrates, lipids, and proteins resulting from defects in insulin secretion, its action, or both." (PMID 27119007, 2016). "Inflammasome activation leads to maturation of caspase-1 and processing of IL1β, contributing to many metabolic disorders and directing adipocytes to a more insulin-resistant phenotype." (PMID 27321128, 2016).
metabolic disorders (continued). "The impact of the TCF7L2 gene on metabolic diseases is fundamental because this gene has multiple targets in the pathways for insulin synthesis." (PMID 27230431, 2016). "On the other hand, although peripheral leukocyte has been widely used for the study of insulin signalling and metabolic disease, we are aware of the potential limitation of this methodology." (PMID 26866272, 2016). "It has also been reported that fenugreek reduces lipid level in plasma and liver leading to the improvement of insulin sensitivity in rats with metabolic disorders." (PMID 27733237, 2016). "Independent of the programming mechanisms, it is important to consider that fluctuations in insulin concentration during perinatal life, including lactation, are a defining factor of later health and metabolic diseases." (PMID 27561682, 2016). "Protein-tyrosine phosphatase 1B (PTP1B) has emerged as an important regulator of insulin signal transduction and is regarded as a pharmaceutical target for metabolic disorders." (PMID 26989693, 2016). "This resonates with our understanding of PCOS as a metabolic disorder underpinned by defects in insulin secretion and sensitivity." (PMID 26859102, 2016). "The AMPK activation in response to calorie restriction and regular exercise increases skeletal muscle fatty oxidation and insulin sensitivity and decreases metabolic disorders." (PMID 27164093, 2016). "Previous studies with a cross-sectional design have documented the relationship between menstrual cycle irregularities, insulin-resistance and the future risks for metabolic disorders." (PMID 27992506, 2016). "In support of this, partial inactivation of PPARγ in PPARγ heterozygotes was found to increase insulin sensitivity, and several pharmacological agents characterized as PPARγ antagonists were shown to ameliorate metabolic disorders." (PMID 27176632, 2016). "It is possible that insulin production in the hypothalamus or other brain areas changes in metabolic diseases." (PMID 26956881, 2016). "Structural defects in insulin can lead to chronic hyperglycemia and metabolic disorders of carbohydrates, proteins, and fat." (PMID 27257845, 2016). "To assess its relevance in metabolic disorders, we investigated if vigilin was deregulated in obese, insulin-resistant mice and measured its expression in livers of diet-induced obese C57Bl/6J (DIO) as well as ob/ob mice." (PMID 27665711, 2016). "Similar to what has been described in metabolic disorders, i.c.v.-injected AβOs induce adipose tissue inflammation and impaired insulin-induced surface translocation of GLUT-4 in muscle cells." (PMID 25617315, 2015). "Exogenous FGF21 administration increased insulin sensitivity in several animal models of metabolic diseases." (PMID 26092866, 2015). "Frequent consumption of fast foods was accompanied with overweight and abdominal fat gain, impaired insulin and glucose homeostasis, lipid and lipoprotein disorders, induction of systemic inflammation and oxidative stress." (PMID 26933642, 2015). "Conditions of metabolic dysfunction increase PTP1B, when deletion of PTP1B protects against metabolic disorders by increasing insulin signaling." (PMID 25974252, 2015). "T1D is a metabolic disease that results from the autoimmune attack against insulin-producing β-cells in the islets of Langerhans of the pancreas." (PMID 25604067, 2015). "Dissecting the regulation of long-term glucose homeostasis via pathways involving both insulin and leptin would be critical to understanding progression of metabolic diseases." (PMID 26540285, 2015). "On the other hand, GDM patients that require insulin therapy to achieve glycemic control have more severe clinical manifestations of the disease and higher risks for metabolic disorders after pregnancy." (PMID 26633694, 2015). "There are some structural defects in insulin itself that lead to chronic hyperglycemia and metabolic disorders of carbohydrate, protein, and fat." (PMID 25177729, 2014).
metabolic disorders (continued). "In this review, we have summarized recent progresses on the links between aging and metabolic diseases, focusing on key signaling pathways such as the insulin/IGF-1 and their tissue specific function in aging." (PMID 24474199, 2014). "These functional and morphological changes in adipocytes were accompanied by impaired activity of the insulin signalling cascade highlighting the important role of different adipose tissue depots in the pathogenesis of metabolic disorders." (PMID 25352910, 2014). "While inhibiting or reducing ROS seems as appealing strategies to treat metabolic disease, it is clear that ROS are necessary for effective and efficient propagation of intracellular signals, including the insulin signalling cascade." (PMID 24672550, 2014). "To assess for disturbances in insulin signaling in Alms1GT/GT mice, we examined the phosphorylation of AKT under basal and insulin stimulated conditions in mice prior to overt metabolic disease at 6 weeks of age." (PMID 25299671, 2014). "In animal models of metabolic disease, there is incomplete recovery of insulin sensitivity after an antioxidant treatment and only partial prevention of NAFLD progression in rats after N-acetylcysteine administration." (PMID 24672550, 2014). "PPARs participate in mediating metabolic disorders via downstream genes which are important for adipocyte maturation, lipid accumulation, and insulin-sensitive glucose transport, including PGC1-α, PGC1-β, aP2, LPL, ACC, ACO, CD36, UCP-2 and Glut4." (PMID 24312343, 2013). "In the context of metabolic diseases, adipokines are not only key mediators in the complex crosstalk between AT with other insulin-sensitive organs such as liver, skeletal muscle, and AT itself, but also have an impact on the cardiovascular system." (PMID 23843684, 2013). "The current studies provide background and initial tools for detailed study of this protein complex in metabolic disease and also suggest a new approach for the discovery and development of potentially more useful and novel insulin sensitizers." (PMID 23690925, 2013). "In 2005, visfatin/Nampt was identified as a novel adipocytokine with suggested beneficial effects in the context of metabolic disorders, as an insulin-mimetic with glucose-lowering properties." (PMID 23843684, 2013). "PPARγ participates in mediating metabolic disorder via numerous downstream adipogenic and lipogenic genes, which are important for adipocyte maturation, lipid accumulation, and insulin-sensitive glucose transport, including FAS, ACC, aP2, SCD-1, and CD36." (PMID 23533476, 2013). "Recent attention drawn by PP2A, in the context of insulin signaling and metabolic disease, has been focused on the inhibitory effects elicited on Akt." (PMID 24150286, 2013). "DM is a group of pandemic debilitating metabolic diseases featuring chronic hyperglycemia which results from defective insulin secretion and/or insulin actions." (PMID 23737866, 2013). "The relationship of 25(OH)D with several markers of metabolic disorder, such as waist circumference, fasting glucose, fasting insulin, triglyceride, HDL cholesterol and LDL cholesterol, remained significant in models adjusted for sex, age and BMI." (PMID 22958612, 2012). "In a cohort of untreated female patients with the simple virilizing form was observed lower insulin sensitivity and higher body weight, blood pressure, and more metabolic disorders, including higher serum TG, and lower HDL-c than the controls." (PMID 23028665, 2012). "Of note, in our study the adiponectin adipose tissue expression appeared as a positive determinant of FABP4 expression, a protein with a predominant role in insulin sensitivity with probable anti-inflammatory activity in metabolic diseases." (PMID 23139800, 2012). "It is also known that visceral adipose percentage, insulin levels, and leptin levels are higher in persons with more severe metabolic disorder." (PMID 22587351, 2012).
metabolic disorders (continued). "Nevertheless, defining PKC as a key regulator of vascular functional response to insulin provides important directions for future experimental and, potentially, clinical studies aiming at preventing vascular complications of metabolic disorders." (PMID 21635764, 2011). "The insulin signaling pathway is of pivotal importance in metabolic diseases, regulator of growth and ageing and can also trigger diapause." (PMID 20939922, 2010). "PPARγ is a member of the ligand-activated nuclear receptor superfamily: its ligands act as insulin sensitizers and some are approved for the treatment of metabolic disorders in humans." (PMID 19043603, 2008). "AMPK is a promising pharmacological target in relation to metabolic disorders partly due to its non-insulin dependent glucose uptake promoting role in skeletal muscle." (PMID 18461163, 2008). "In consonance, impairment of insulin and glucose metabolism by ERβ has significant implications for our understanding of hormone receptor-dependent pathophysiology of metabolic diseases, and is essential for the development of new ERβ-selective agonists." (PMID 18584035, 2008). "Diabetesmellitus is a heterogeneous metabolic disorder diagnosed by hyperglycemiaresulting from impaired insulin secretion, resistance to insulin action, orboth." (PMID 18923682, 2008). "These alterations may impair insulin signaling through lipid raft modulation and correlate with metabolic disorders." (PMID 41517237, 2026). "Additionally, studies have reported that TNF‐α gene knockout improves insulin sensitivity in obese mice, suggesting its central role in metabolic disorders." (PMID 41388732, 2026). "In light of the critical role of bile acids in metabolic regulation and the therapeutic potential of acupuncture for endocrine–metabolic disorders, this study aims to explore the effects of acupuncture on bile acid metabolism and insulin sensitivity in both PCOS patients and rat models." (PMID 41514462, 2026). "Therefore, understanding the interplay between SeP, insulin resistance, and liver function provides key insights into the pathophysiology of metabolic disorders and highlights SeP as a potential biomarker and therapeutic target." (PMID 41341131, 2025). "T2DM is a progressive metabolic disorder that arises from compromised insulin responsiveness in specific target tissues, including the liver, skeletal muscle, and adipose tissue, alongside inadequate insulin synthesis by pancreatic β-cells." (PMID 40078364, 2025). "BCAAs can also impair insulin-stimulated glucose uptake in skeletal muscle and inhibit insulin-induced phosphatidylinositol 3-kinase activity, leading to impaired glucose uptake, insulin resistance, and subsequent metabolic disorders." (PMID 40036545, 2025). "Considering the important role of SWELL1 in regulating insulin sensitivity and cell proliferation, it may play a crucial bridging role between metabolic disorders and cancer." (PMID 40191429, 2025). "T2D is a metabolic disorder characterized by altered response to insulin." (PMID 41300761, 2025). "Since the kidneys play a critical role in insulin metabolism, kidney dysfunction means insulin is not fully metabolized, leading to elevated insulin levels and increased risk of metabolic disorders." (PMID 41040857, 2025). "A mutated or downregulated expression of CELA2A may therefore affect insulin secretion/degradation/sensitivity and can be considered important for metabolic disease." (PMID 40652086, 2025). "Low, as many patients with early metabolic disease remain within “normal” insulin ranges." (PMID 41586225, 2025). "IR is a distinctive metabolic disorder, typically characterized by elevated insulin levels." (PMID 40078639, 2025). "Moreover, phosphorylation of REPS1 strongly correlated with insulin sensitivity and was specifically impaired in skeletal muscle under insulin-resistant conditions, emphasizing its potential relevance in metabolic diseases such as T2D." (PMID 40482643, 2025).
metabolic disorders (continued). "The binding of OTA to INS may disrupt insulin signaling, leading to metabolic disorders and increased cell proliferation." (PMID 40864064, 2025). "To compensate, pancreatic β-cells increase insulin secretion, maintaining normoglycemia in the early stages, but this compensation may eventually fail, contributing to the progression of metabolic disorders." (PMID 39942757, 2025). "This age difference may be attributed to the protective influence of oestrogen on metabolic disorders in premenopausal women, as oestrogen helps regulate lipid metabolism, insulin sensitivity, body composition and fat distribution." (PMID 40140729, 2025). "Metabolic disorders may lead to cell membrane disruption and increased lipotoxicity, triggering β-cell apoptosis or dysfunction and reducing insulin secretion." (PMID 40732347, 2025). "Enrichment in pathways like ErbB, insulin signaling, and focal adhesion aligns with CMap predictions, suggesting potential for repurposing these inhibitors in neurodegenerative diseases, fibrosis, and metabolic disorders." (PMID 40732226, 2025). "These quantitative findings justify considering liposome-in-hydrogel formats when the target is oral or mucosal delivery of peptides (e.g., insulin) or when both systemic bioavailability and sustained local action are required in metabolic disease interventions." (PMID 41294602, 2025). "Its importance in metabolic diseases is highlighted by its role in insulin production." (PMID 41226319, 2025). "We therefore speculate that DKK1 may act as a negative regulator of metabolic disorders and insulin sensitivity." (PMID 41320970, 2025). "Increasing evidence suggests that neuroinflammation may contribute to insulin resistance in the brain, thereby linking metabolic disorders to neurodegeneration." (PMID 40871707, 2025). "Similarly, elevated IL-6 and IL-1β have been shown to reduce insulin effectiveness by interfering with insulin signaling pathways, further promoting metabolic disorders and elevated blood glucose." (PMID 40351422, 2025). "By clarifying the regulation and pathology of GSVs, researchers may uncover novel therapeutic targets capable of restoring insulin sensitivity and mitigating metabolic disease progression." (PMID 40806697, 2025). "In metabolic diseases like obesity, microglial dysfunction disrupts the inhibitory/excitatory balance of AgRP-pancreatic neural projections, leading to abnormal insulin secretion—an effect that complements the metabolic dysregulation caused by HPA axis dysfunction." (PMID 41294833, 2025). "While much is known about HMOX, little is known about BVR and bilR and how they may regulate insulin signaling and fat accumulation to control metabolic diseases, and more studies should reveal their importance in the future." (PMID 39873298, 2025). "EOs can enhance insulin sensitivity and ameliorate metabolic disorders." (PMID 41199858, 2025). "Additionally, the role of insulin in the reproductive system, including ovarian function, should be investigated in order to understand fertility issues and reproductive health in metabolic disorders." (PMID 40725728, 2025). "Although sphingolipids, specifically ceramides, are not the most abundant lipids in mammalian cells, the accumulation of ceramides in insulin-sensitive tissues and the islets of Langerhans during insulin toxicity is believed to play a crucial role in the onset and progression of metabolic disorders." (PMID 40137159, 2025). "Propionylcarnitine (C3) serves as a crucial diagnostic marker for congenital fatty acid oxidation disorders and an important indicator for physiological processes such as energy metabolism, mitochondrial and peroxisome β‐oxidation activity defects, insulin resistance, and metabolic disorders." (PMID 40391686, 2025).